IL6 (interleukin 6)
Diseases named in the same sentence as IL6 in open-access papers (continued):
Sharing a sentence is not in itself a finding about the gene and the disease.
tumor (continued). "In turn, tumor glia promote monocyte differentiation towards pro-tumorigenic SPP1+ tumor-associated macrophages by IL-6 release." (PMID 39030280, 2024). "STAT3, originally identified as an acute phase response factor to IL‐6, has been well demonstrated to be associated more frequently than other STATs with tumour formation." (PMID 39099000, 2024). "In chronic inflammation caused by cancer cachexia, inflammatory cytokines such as TNF-α and IL-6 promote muscle loss and tumor growth." (PMID 39272894, 2024). "Mice exposed to sevoflurane exhibit elevated levels of proinflammatory cytokines triggered by the activation of the IL-6/JAK/STAT3 pathway that is associated with tumor metastasis." (PMID 39001366, 2024). "Pro-inflammatory ILs like IL-1, IL-6, and IL-17 have been linked to the stimulation of osteoclastogenesis and tumor proliferation, thereby influencing critical aspects of bone metastasis processes." (PMID 39125732, 2024). "We next analyzed the protein and gene expression levels of IL-6 and PTHrP in tumors because low food efficiency and AT depletion were observed in tumor-bearing mice and as IL-6 and PTHrP, known as tumorkines, are mediators in fat depletion." (PMID 39273055, 2024). "The IL-6, IL-31, and IL-1RA predictions were primarily associated with tumor extent and smoking history, whereas the soluble receptors (s)-IL-6Rα, s-gp130, and s-IL-33Ra predicted survival even after such adjustments." (PMID 38672565, 2024). "This phenomenon is promoted in part via the production of IL-6-loaded Exos via cancer cells that dictate specific phenotypes for tumor-associated macrophages (TAMs)." (PMID 38360641, 2024). "Elevated CRP levels likely reflect ongoing inflammatory responses, while IL-6, a proinflammatory cytokine, has been implicated in tumor growth, angiogenesis, and immune evasion." (PMID 39816276, 2024). "Studies have shown that tumor cells can release cytokines such as IL-6, IL-10 and TGF-B that cause dendritic cells to remain in an immature or immunosuppressive stage." (PMID 39108491, 2024). "While elevated levels of certain cytokines like IL-6, IL-8, and TGFβ are associated with poor prognosis, there exist key cytokines that restrain tumor proliferation through anti-proliferative effects or by promoting cytotoxic activities." (PMID 38785789, 2024). "IL6 is one of the well-characterized pro-tumorigenic cytokines associated with tumour-associated inflammation and tumorigenesis in HCC." (PMID 38840185, 2024). "In another murine model of colitis-associated CRC, anti-IL-6 antibody treatment significantly inhibited tumor growth and was associated with downregulation of the pleiotropic transcription factor HIF-1α." (PMID 38689325, 2024). "Amongst various secretory factors, IL-6 was found to be associated with resistance towards chemo- and radiotherapy, besides promoting tumor growth." (PMID 38957610, 2024). "Using multiple KRAS-driven human LUAD cell lines, our work demonstrates that STK11 loss results in altered tumor-intrinsic cytokine expression, including but not limited to IL-6, CXCL8 and CXCL2." (PMID 37968341, 2024). "Elevated serum levels of IL-6 and IL-8 are associated with multiple tumour types, including melanoma, lung, oral (squamous), and gastric cancers." (PMID 39676864, 2024). "Gain- and loss-of-function experiments revealed that VPS35 promoted tumour proliferation and metastasis via the IL-6/STAT3 pathway." (PMID 37950040, 2024). "For instance, high-risk HPV-infected cells enhance IL-6 expression, which modulates the tumor immune microenvironment via paracrine signaling transduction." (PMID 39095779, 2024). "Imbalance of gut microbiota can lead to activation of tumor associated macrophages (TAMs), thereby promoting the secretion of IL-6." (PMID 38751718, 2024). "IL6 can impact on neighbouring tumour cells via the IL6 cytokine receptor, causing activation of JAK and STAT3 signalling leading to changes in gene expression and cellular proliferation." (PMID 38535967, 2024).
tumor (continued). "They play a pivotal role in shaping the polarization of tumor-associated macrophages (TAMs) towards an immunosuppressive M2 phenotype, potentially facilitated by cytokines like IL6, thereby exacerbating HCC progression." (PMID 38791916, 2024). "For instance, interleukin-6 (IL-6) and IL-8 have been implicated in promoting osteoclastogenesis and enhancing tumor cell survival." (PMID 39770433, 2024). "In biopsy specimens of smoking patients, we found a significant association of CD44, KRT4, and KRT13 expression with IL6 gene expression, the level of which was increased in tumor tissue of smokers compared to peritumor tissue." (PMID 38540309, 2024). "The proinflammatory microglia produced high concentrations of nitric oxide (NO) and high levels of the proinflammatory cytokines TNF-α, IL-6, and IL-1β, and caused further DNA damage and promoted the apoptosis rate of tumor cells." (PMID 38750472, 2024). "The overexpression of IL-6 reduces serum lipid levels and has been linked to advanced tumor grades, larger tumors, poor responses to chemoradiotherapy, and shorter survival time in OSCC." (PMID 39767804, 2024). "To identify the source of tumour‐associated IL‐6, we measured protein levels across tissues and found that pancreas/tumour tissue had the largest increase in IL‐6 protein between sham and OT‐PDAC mice." (PMID 38632714, 2024). "Among the plethora of TGFβ-induced cytokines, interleukin 6 (IL-6) is the best known to be linked to an increased risk of developing a wide variety of tumor histotypes." (PMID 39015505, 2024). "For instance, the interleukin-6 (IL-6) signaling pathway has been implicated in promoting tumor growth and immune evasion in various cancers." (PMID 39916959, 2024). "Because macrophage‐secreted IL‐6 is involved in tumour progression, we decided to determine the effect and underlying mechanism of calycosin action on IL‐6 production in macrophages." (PMID 37974543, 2024). "A similar study in n = 209 CRC patients showed results concordant with this study, implicating high levels of IL6 within the tumour-associated stroma with worse outcomes." (PMID 39766336, 2024). "Elevated IL-6 expression has been shown to stimulate tumor growth and is associated with metastasis in the majority of cancer cases." (PMID 39594832, 2024). "In vitro analyses support the assumption that interleukin 6 (Il-6) contained in the exosomes and the micro-RNA 155-3p support autophagy and the associated tumor-promoting phenotype of macrophages." (PMID 39062119, 2024). "At the same time, our results show that a higher efficacy of anti-IL-6 therapy can be expected in a cohort of smoking patients, where this cytokine plays an important role and interacts with a number of other tumor-associated genes." (PMID 38540309, 2024). "Similar to our study, IL-6 expression was linked to tumour stages and levels of prostate-specific antigen (PSA)." (PMID 39554609, 2024). "Elevated IL-6 expression has been correlated with poorer outcomes in cancer patients and is often linked to advanced tumor stages." (PMID 39594709, 2024). "The combined use of IL-6 with the traditional tumor marker CEA showed significant diagnostic performance in our analysis of 300 serum samples.While our findings are promising, validation across larger and more diverse samples is necessary." (PMID 38529301, 2024). "The exosomal cSERPINE2 from tumor cells acts on the tumor‐associated macrophages and promotes the secretion of IL‐6, thereby accelerating the proliferation and metastasis of breast cancer cells." (PMID 39584047, 2024). "Factors associated with the tumor microenvironment (IL-10, IL-6) hinder the differentiation of DCs, decrease their maturation, and suppress T cell activation." (PMID 38426090, 2024). "Hepatic infiltration and activation of MDSCs can be regulated by inflammatory chemokines (e.g., CXCL1 and CCL2) and cytokines (e.g., IL-6), tumor-associated fibroblasts, epigenetic factors, and gut microbiota during liver pathogenesis." (PMID 38397901, 2024).
tumor (continued). "myCAFs are linked to focal adhesion and interactions with the extracellular matrix, showing evidence in enhancing the stemness of tumor cells by secreting senescence-associated secretory phenotype factors IL-6 and IL-8 to resist chemotherapy." (PMID 39524442, 2024). "We report here that E2F1 physically interacts with active STAT3 and synergistically controls IL-6 expression to induce a tumor-associated inflammatory GRN that ultimately mediates metastatic traits and modulates the TME by releasing immunomodulatory factors." (PMID 39544930, 2024). "Increased IL-6 production can shift intestinal macrophages towards a M2-like macrophage phenotype in mouse models which overlaps with tumour-associated macrophages." (PMID 38248845, 2024). "Consistent with the dual BCL2/MYC translocation association with poor patient outcomes, VAL cells showed heightened proliferation in human IL6-conditioned media and caused rapid tumor expansion and early death in the engrafted mice." (PMID 39272864, 2024). "Interleukin-6 (IL-6) is an inflammation-associated CK with a high expression level associated with PCa aggressiveness, tumor growth, and poor prognosis." (PMID 40353136, 2024). "Primary sources of IL-6 secretion within the tumor microenvironment include tumor cells and tumor-associated fibroblasts." (PMID 39738201, 2024). "High plasma IL-6 is therefore associated with a worse prognosis as it leads to increased tumour cell proliferation and metastasis." (PMID 38468349, 2024). "Metastasis of the LLC also involves the powerful stimulation of tumor-associated macrophages, which produce IL-6 and TNFα by activating TLR-2 and TLR-6." (PMID 38891915, 2024). "CXCL7 from MSCs interacts with cancer cells via the IL-8 receptor, also known as C-X-C chemokine receptor type 2 (CXCR2), causing tumors to further synthesize IL-6 and IL-8 (another cytokine involved in tumor-tropism)." (PMID 38169524, 2024). "Studies suggest that activation of different interferon genes in breast cancer cells induces the expression of an IL6-associated signaling cascade that promotes tumor progression." (PMID 39201585, 2024). "Recent studies have demonstrated that tumor-associated SCs secrete elevated levels of IL-6 across various tumor types, which is linked to immune regulation, tumor progression, and the perception of injury." (PMID 39769484, 2024). "Several relative experiments showed that TNF‐α and IL‐6 declined apparently in the serum of cancer cells in mice after intragastric omeprazole which implied that PPIs inhibit the tumour progression caused by fat metabolism." (PMID 35961680, 2023). "Tumor-associated macrophage (TAM)-derived IL-6 is involved in small-cell lung cancer (SCLC) progression and chemoresistance via the activation of signal transducer and activator of transcription 3 (STAT3) in the tumor microenvironment." (PMID 36961655, 2023). "In the tumor microenvironment, IL-6 can be produced by various cells, including tumor-associated macrophages, granulocytes, and tumor cells, which are its main sources." (PMID 37817809, 2023). "PT increased tumor cell death associated with increased DNA damage, and IL6 and HMGB1 expression compared with sham irradiation." (PMID 36672266, 2023). "In this study, we observed that the anti‐tumour effects of KO mice were closely associated with IL‐6 expression from NPs and MPs." (PMID 36419386, 2023). "In patients with advanced ovarian cancer, serum IL-6 levels were inversely correlated with Hb levels, and high serum IL-6 levels were attributed to M1 tumor-associated macrophages from the tumor microenvironment." (PMID 37208766, 2023). "Accumulating evidence suggests that inflammatory signals from tumor cells and the surrounding microenvironment, such us IL‐6, are strongly associated with promote tumor growth in several cancer types." (PMID 37326149, 2023).
tumor (continued). "In a cohort of advanced NSCLC treated with pembrolizumab (cohort# 2), we demonstrated that tumor IL-6 expression was associated with lower ORR and PFS." (PMID 37852738, 2023). "Tumor-associated macrophages (TAMs) promote tumor progression in liver tissue microenvironments by releasing IL-6, which, in turn, activates the IL-6/STAT3 signaling pathway in nearby HCC stem cells." (PMID 37892997, 2023). "OSM, like IL-6, has been linked to tumor growth and is often found in high concentrations in the serum and tumor sites of patients and animal models of cancer." (PMID 37961653, 2023). "Cetuximab repolarized tumor-associated macrophages (TAMs) from M2-like to M1-like phenotypes, mainly by suppressing the IL-6 expression through NF-κB and STAT3 pathways." (PMID 37143088, 2023). "This process is mediated by IL-6 which contributes to the recruitment of tumor-associated macrophages of the M2 immunosuppressive subtype, which in turn, upregulates anti-inflammatory cytokines including IL-10 and TGF-β." (PMID 38188300, 2023). "Recently, research has suggested that IL-17A-mediated neovascularization is inextricably linked with the IL-6/STAT3 pathway in animal tumor models." (PMID 36873773, 2023). "Taken together, our study reveals an IFN-triggered IL-4/IL-6 cytokine network impacting on the phenotypes of tumor-associated macrophages." (PMID 36726024, 2023). "IL-6 plays a crucial role in immunoregulation and in tumor progression, and its overproduction is generally associated with dismal prognosis." (PMID 37958430, 2023). "The tumorigenic effects of IL-6 involve the conversion of tumor-associated macrophages from an M1-type phenotype with anti-tumor properties to an immunosuppressive M2-type phenotype." (PMID 37907991, 2023). "Rapid and excessive IL-6 production caused by cytokine release syndrome (CRS) promotes tumor invasion, proliferation, and angiogenesis along with the development of an amplifying loop for inflammation." (PMID 37488213, 2023). "Our findings indicate that a high level of IL-6 in MBC patients is associated with a pro-inflammatory tumor microenvironment, which promotes recruitment of MDSCs and suppresses anti-tumor immunity, including CD8+ lymphocyte activity." (PMID 37733188, 2023). "By acting in a paracrine manner, ASCs accelerate tumor growth in co-cultures with cancer cells and stimulate the secretion of interleukin-6 in ASCs, which in turn causes the cancer cells to enhance their malignant properties in a paracrine manner." (PMID 37235430, 2023). "Previous studies have demonstrated that EMT activation, angiogenesis, and IL-6/JAK/STAT3 pathways increase the risk of tumor invasion, metastasis, and drug resistance." (PMID 37874419, 2023). "Inositol-requiring enzyme 1 alpha (IRE1), which has RNase and kinase activities, has been associated with tumor progression and recently was found to regulate the production of cytokines such as IL-6 and IL-8 after treatment with paclitaxel." (PMID 36768435, 2023). "In parallel, higher IL-6 levels are associated with increasing tumor stages, tumor sizes, metastasis, and reduced cancer survival." (PMID 36975471, 2023). "In this review, we will focus on the interactions between MCs, NK cells, and neuronal structure and their communications via proinflammatory cytokines, including TNFα, IL-1β, and IL-6, in peripheral neuropathy in association with tumor immunology." (PMID 37628724, 2023). "While it primarily promotes tumor growth and progression, IL-6 also exhibits paradoxical effects under specific contexts, often linked to the tumor microenvironment and stage." (PMID 37892997, 2023). "Tumor-associated fibroblasts (CAFs) also facilitate the production of MDSCs by activating IL-6/STAT3 pathway." (PMID 36845131, 2023).
tumor (continued). "In this context, prostate cancer patients with a higher depression score had higher CD68+ tumor-associated macrophage infiltration and interleukin-6/NPY expressions." (PMID 37373115, 2023). "In VHL-deficient RCCs, IL-6 production is increased, which propagates macrophage migration to the tumor site and polarization toward an M2-like phenotype." (PMID 37190141, 2023). "IL-6 also has been shown to directly cause cachexia through a cross-talk mechanism between tumor, muscle, and fat requiring IL-6 signaling." (PMID 38022578, 2023). "High levels of IL-6 promote tumor invasiveness, and it is strongly associated with reduced response to sunitinib and pazopanib in patients with metastatic RCC." (PMID 37190141, 2023). "The pleiotropic cytokine IL-6 is associated with tumor progression and is supposed to affect anti-tumor immunity through a variety of mechanisms." (PMID 37240834, 2023). "The percentage decrease in serum let-7a and the percentage increase in serum IL-6 levels at the early stage of radiotherapy were inversely associated with tumor regression after radiotherapy." (PMID 38114473, 2023). "The tumor and tumor-associated cells secrete several factors that impair NK cells activation, such as IL-6, TGF-B, PGE2, and IDO." (PMID 36260158, 2023). "IL-6 is reportedly secreted by tumor cells and cancer-associated fibroblasts in response to platinum treatment, enhancing chemoresistance via STAT3-mediated enrichment of cancer stem cells." (PMID 37124547, 2023). "The association was validated for IL-6 (HR = 1.25, 95% CI 1.08–1.46) and IL-15 (HR = 2.23, 95% CI 1.48–3.35) in an independent cohort adjusting for PS, tumor location, and stage." (PMID 36831406, 2023). "A series of cytokines, including TNF-α and IL-6, have been associated with the differentiation and proliferation of tumor cells and tumor neoangiogenesis in CRC." (PMID 38068319, 2023). "IL-4, IL-13, IL-10, IL-6, and colony stimulation factor 1 (CSF-1) all contribute towards M2 polarization of tumor-associated macrophages (TAMs)." (PMID 37173951, 2023). "Tumor cells are able to stimulate miR-214 expression in the stroma counterparts which is linked to IL-6 production and IL-6/STAT3 signaling." (PMID 36639824, 2023). "The pleiotropic cytokine interleukin 6 (IL-6) is associated with tumor progression and is thought to influence anti-tumor immunity through various mechanisms." (PMID 36599350, 2023). "For instance, increased CIN, as is caused by MCAK inhibition, has been shown to trigger IL-6 signaling through cGAS-STING to increase tumor cell survival." (PMID 37444419, 2023). "IL-6 is associated with tumor growth, differentiation, apoptosis, drug resistance, and immune regulation." (PMID 36990991, 2023). "In BC, upregulation of serum IL-6 levels is associated with poor prognosis (Refs 91, 92), where hormone-sensitive tumour cells have a greater response to IL-6 (Ref." (PMID 37009688, 2023). "Release of IL-1, IL-4 and IL-6 from mast cells was associated with elimination of tumour cells and rejection of tumours." (PMID 38137361, 2023). "For CRP, PCT and IL-6, it is notable that many factors can cause changes in their levels during tumor removal, including surgical stress and anesthesia." (PMID 37194025, 2023). "Tumor-associated stromal cells recruit tumor cells and tumor promoting cells by secreting tumor promoting factors such as IL-6 and IL-814." (PMID 36869083, 2023). "In gastric tumors, GC-MSCs trigger the conversion of macrophages into the M2 subtype of tumor-associated macrophages (M2-like TAMs) by secreting IL-6 and IL-8 and via the activation of the JAK2/STAT3 signaling in macrophages." (PMID 37189649, 2023). "This invasive form of p-FoxM1 upregulates the expression of IL1A/1B, VEGFA, and IL6 by direct activation, recruiting monocytes and promoting the polarization of M2d-like tumor-associated macrophages (TAMs)." (PMID 37968723, 2023).